TLR9 (toll like receptor 9)
Diseases named in the same sentence as TLR9 in open-access papers (continued):
Sharing a sentence is not in itself a finding about the gene and the disease.
tumor (continued). "used a mouse model showing that pre-existing STAT3 in myeloid cells that contribute to tumors such as MDSCs can considerably direct the TLR9 signaling process to the tumor angiogenesis and inhibition of antitumor immune responses." (PMID 33679700, 2020). "In the context of failed therapeutic applications, the expression of TLR9 on tumor cells and the consequences of TLR activation on cancer cells have received increasing attention." (PMID 32483468, 2020). "We first treated mice bearing subcutaneous Hepa1-6 tumors with ODN1585 (a murine TLR9 agonist) or an anti-PD-1 antibody alone or in combination and monitored tumor growth." (PMID 32483468, 2020). "We found that OCT4-3 + TLR9 significantly inhibited tumor growth compared with the PBS control group." (PMID 32296581, 2020). "These IFNs play a critical role in TLR9-mediated antitumor responses because they are involved in activation of the adaptive immune response required for tumor-cell killing." (PMID 32547560, 2020). "These authors demonstrated that during hypoxia, HMGB1 translocates from the nucleus to the cytosol, where it binds to DNA released from damaged mitochondria, resulting in activation of intracellular TLR9 and tumor cell proliferation." (PMID 32664328, 2020). "In prevention assays, significant tumor growth inhibition was achieved in BABL/c mice treated with OCT4-3 + TLR9 (P < 0.01)." (PMID 32296581, 2020). "A melanin-based vaccine in combination with a TLR9 has also proved to be a strong anti-tumor efficacy in cancer murine models and compares favorably with the classical formulation of IFA and TLR9 agonist." (PMID 33679703, 2020). "The tumor weights and images of tumors of each group also indicated the significant advantages of OCT4-3 + TLR9 in suppressing tumor growth." (PMID 32296581, 2020). "Depending upon tumor cell types, TLR9 activation can stimulate or inhibit tumor cell proliferation or induce caspase-dependent apoptosis." (PMID 33679703, 2020). "It has been demonstrated that TLR9 agonist effectively increases tumor infiltration by CD8+ T cells." (PMID 32813937, 2020). "The tumor weights were significantly decreased in the OCT4-3 + TLR9 vaccine group in the treatment experiment." (PMID 32296581, 2020). "Based on the positive results of preclinical studies showing that TLR9 activation can induce adjuvant effects to promote T-cell activation and reduce tumor burden, CpG-ODNs have been investigated in clinical trials as therapeutic antitumor agents." (PMID 32547560, 2020). "Similar to data obtained in this study, upregulated expression of TLR9 in HNSCC as well OSCC was found to promote tumor cell invasion, proliferation as well as migration by enhancing MMP-2 expression." (PMID 32961854, 2020). "Drug-induced activation of TLR9 was proven to moderately improve immunogenic tumor sensitivity and augment innate immunity to promote tumor regression, thus indicating plausible potential synergetic effects between TLR9 agonist and PD-1 inhibitors." (PMID 32695664, 2020). "For example, a novel strategy combining STAT3 ASO with TLR9 stimulation (CpG oligonucleotide) has been shown to enhance the anti-tumor immunity and overcome tumor immune tolerance in prostate cancer." (PMID 32972405, 2020). "TLR-9 can enhance anti-tumor immunity by recognizing Oligodeoxynucleotide(ODN) containing cytosine–guanine dinucleotide (CpG), which is a potential therapeutic agent." (PMID 33469538, 2020). "Tumor-induced down-regulation of TLR9 expression has been identified as one leading mechanism of pDC dysfunction within the tumor environment." (PMID 32054102, 2020). "Some in vitro studies demonstrated that TLR9 stimulation can induce PD-L1 expression in mouse tumor cells." (PMID 31892973, 2020). "In our whole population-based study of NPC in Finland, we examined the expression of TLR1, TLR2, TLR4, TLR5, TLR7, and TLR9 in 150 tumours and analysed their pattern of expression according to EBV and HPV status, and clinical outcome." (PMID 31238894, 2019).
tumor (continued). "We thus decided to explore the role of TLR9 in this process by inoculating either wildtype C57BL/6 or TLR9−/− mice with TC-1 tumor cells." (PMID 31619293, 2019). "Specifically, the TLR9 agonists CpG-oligodeoxynucleotides (ODNs) are being explored in a wide range of tumor types, both as single agents and as adjuvants, and are being tested in several clinical trials." (PMID 30921319, 2019). "In contrast, ratios of CD8 T cells to myeloid-derived suppressor cells (MDSC) benefitted most from the combination of TLR9 agonist delivered to the right flank tumor combined with systemic PD-1 blockade." (PMID 31771649, 2019). "There have been a few reports showing that combination of a TLR9 agonist CpG-ODN with CY results in anti-tumor effects in mouse tumor models." (PMID 31921384, 2019). "We next looked into the mechanisms by which TLR9 contributes to the anti-tumor immune response after chemotherapy." (PMID 31619293, 2019). "Tumor DCs from wildtype mice had higher average expression of CD40 and CD80 compared to DCs from TLR9−/− mice, suggesting that host TLR9 promotes the maturation of tumor DCs." (PMID 31619293, 2019). "Prior publications have demonstrated the potential of various TLR9 agonists administered via intra-tumor injection to augment anti-tumor immunity alone or in combination with T cell checkpoint blocking or T cell co-stimulatory agonist antibodies." (PMID 31771649, 2019). "One of the possible approaches is to stimulate producers of IFNα at the tumor site via the intralesional application of TLR9 and TLR7 ligands." (PMID 30987228, 2019). "Since TLR9 is predominately found on professional antigen presenting cells (APC), we examined the influence of TLR9 on tumor DCs." (PMID 31619293, 2019). "Another study proved, in the animal models, that tumor therapeutic vaccine compound of TLR9 agonists (CpG ODN) and irradiated tumor cell tracking of two other CpG ODNs injections lead to a long-term antitumor immune response against aggressive tumors." (PMID 31886298, 2019). "In this sense, we have shown that TLR4 expression by MICs was associated with an increased incidence of metastasis, whereas TLR9 expression by CAFs was associated with a low metastasis-rate, pointing towards a protective role of TLR9 against tumor progression." (PMID 31086100, 2019). "Evaluation of the tumor growth and survival was performed in mouse strains having a different immunological background (C57Bl/6 (WT), nude and C57Bl6 (TLR9−/−))." (PMID 31242938, 2019). "We show here that host Toll-like receptor 9 (TLR) acts as a sensor for extracellular DNA shed from dying tumor cells and is critical for the adjuvant effect of chemotherapy." (PMID 31619293, 2019). "TGF-β also promotes the conversion of tumor associated pDCs into a suppressive phenotype by inhibiting IFN-α and MHCI expression in cells activated by the toll like receptor 9 (TLR9) agonist, CpG." (PMID 31921140, 2019). "Altogether, these data show that host TLR9 is essential for the anti-tumor immune response following chemotherapy." (PMID 31619293, 2019). "E7-specific CTL response were markedly reduced in TLR9−/− TC-1 tumor-bearing mice treated with chemotherapy and E7 peptide injection compared to wildtype mice, suggesting that host TLR9 influences the adaptive immune response generated by chemotherapy." (PMID 31619293, 2019). "In this study, we found that host TLR9 acts as a sensor for tumor DNA that modulates the anti-tumor immune response following chemotherapy." (PMID 31619293, 2019). "Here, employing three tumor models, we report that prophylactic systemic treatment with CpG-C, a TLR9 agonist, exerts beneficial effects through reducing tumor cell seeding and growth in the brain." (PMID 30921319, 2019). "Aberrant expression of TLR9 in tumor cells was shown to be able to promote tumor growth and invasion." (PMID 31205871, 2019).
tumor (continued). "TLR9 injected tumors on the right flank largely resolve; however, resolution of the left flank tumor is only pronounced in combination with CTLA-4 blockade." (PMID 31771649, 2019). "Clinical trials with IMQ and a DNA-based TLR9 immunomodulator in metastatic cancer also showed histological tumor regression and an increase in lymphoid immune infiltration." (PMID 31547627, 2019). "We treated wildtype or TLR9−/− TC-1 tumor-bearing mice with cisplatin intraperitoneally together with FITC-labeled E7 peptide by intratumoral injection." (PMID 31619293, 2019). "We show that this ‘adjuvant effect’ of chemotherapy is, at least partially, mediated by the release of tumor DNA and acts through the Toll-like receptor 9 (TLR9) pathway." (PMID 31619293, 2019). "Here, the synergistic effect of a TLR2-neutralizing antibody and a TLR9 agonist CpG ODN was observed to advance coherent immunotherapy against tumor metastasis." (PMID 31508424, 2019). "When activated by CpG binding, TLR9 facilitates immunostimulatory signaling and the release of proinflammatory cytokines as well as the presentation of tumor-specific antigens." (PMID 31671769, 2019). "The TLR9 mRNA expression was inversely correlated with tumor size (p = 0.014; r = −0.314) at diagnosis." (PMID 31886298, 2019). "Since the viral proteins are present in NPC tumor cells, they can inhibit and degrade the TLR9 mRNA." (PMID 31886298, 2019). "More relevant to time of day, some inflammatory mediators (Myd88, Cd4, Tlr9, Cd38, C3, Ly96) demonstrated nyctohemeral (day versus night) differences in control brain tissues that were abolished in tumor-bearing and/or tumor-resected mice." (PMID 31019214, 2019). "In animal model of prostatic cancer it has been shown that expression of TLR9 on tumor cells has the tumor-propagating potential." (PMID 30976817, 2019). "We found that TLR9 signaling triggers the accumulation, maturation, and lymph node migration of antigen-loaded tumor dendritic cells (DCs)." (PMID 31619293, 2019). "Tumors (Cd4, tendency in Myd88, p = 0.07) and tumor resection (Myd88, Cd4, Tlr9, Cd38) eliminated these time-of-day differences by reducing light-phase gene expression relative to controls and or increasing dark phase expression." (PMID 31019214, 2019). "Several studies are interested in examining the effect of combining RT with TLR9 stimulation on antitumoral immunity, primary tumor growth retardation." (PMID 31886298, 2019). "These antimetastatic effects involve BV directly activating NK cells by inducing the upregulation of NK cell effector function against the tumor in a Toll-like receptor 9 (TLR9)-dependent manner." (PMID 31649751, 2019). "Our novel results suggest that HPV-positive HNSCC enlist fibroblasts and generate a tumor-permissive microenvironment via TLR9-mediated engagement of PD-1/PD-L1/PD-L2 pathways." (PMID 31379843, 2019). "Upon the treatment, TLR9-expressing myeloid cells (in particular, PMN-MDSC) displayed a decreased immunosuppressive activity, whereas TLR9-positive tumor cells lost the resistance to apoptosis via the STAT3 signaling." (PMID 29552012, 2018). "TLR9 recognizes unmethylated CpG DNA and promotes the production of inflammatory cytokines that contribute to tumour immunity." (PMID 30147445, 2018). "It has been reported that oligodeoxynucleotides targeting TLR9 oppositely modulate DNA repair genes in tumor versus immune cells and enhance the antitumor activity of DNA-damaging chemotherapy and radiation therapy in preclinical mouse models." (PMID 29883450, 2018). "In a murine model of ovarian cancer, immunization with microparticles containing ligands of TLR9 and nucleotide‐binding oligomerization domain 2 leads to the accumulation of T cells in the tumours and prolongs the survival of tumour‐bearing mice." (PMID 29963704, 2018).
tumor (continued). "Combined treatment with α-GalCer-loaded tumor cells and cytosine-phosphorothioate-guanine (a TLR9 agonist) in a mouse colorectal cancer model led to tumor growth inhibition and prolonged survival." (PMID 29773994, 2018). "For example, CpG-rich oligonucleotides, which engage endo/lysosomal Toll-like receptor 9 (TLR9) and are employed in clinical trials to boost anti-tumor responses, on an equimolar base exerted much stronger APC stimulation when coupled to a NC." (PMID 30116246, 2018). "In murine model, TLR9 agonist has been shown to enhance therapeutic effects of radiation by increasing tumor-infiltration of natural killer dendritic cells, which led to fewer metastases and longer survival." (PMID 30558196, 2018). "We demonstrate that despite the inability to trigger TLR9, doggybone DNA was able to induce similar levels of cellular and humoral immunity as plasmid DNA, with suppression of established TC-1 tumours." (PMID 29330557, 2018). "Our recent study in preclinical solid tumor models in mice demonstrated that localized tumor irradiation results in release of DAMPs, including Toll-like Receptor 9 (TLR9) ligands, recognized by myeloid immune cells, such as macrophages and MDSCs." (PMID 29541413, 2018). "Third, some studies have indicated that CpG can react with tumor cells expressing TLR9, aiming to induce tumor cell autophagy." (PMID 30120629, 2018). "TLR9 on plasmacytoid dendritic cells are involved in secretion of type I interferons that are involved in anti-tumor immunity." (PMID 28174608, 2017). "Investigating the influence of TLR9-dependent activation of immune cells during the tumor development, mice were treated with CpG ODN 2216 (CpG)." (PMID 28191009, 2017). "For example, TLR9 agonists, which have already been added to anti-cancer strategies such as chemotherapy, radiotherapy and immunotherapy, are able to enhance the anti-tumor immune response mediated by T and B cells." (PMID 28632155, 2017). "Peritumoral injection of CpG oligodeoxynucleotides, a TLR-9 agonist used in clinical trials to improve immunotherapy, resulted in tumor directed migration of primed DCs that show enhanced phagocytosis, maturation and antigen presentation to T-cells." (PMID 28218708, 2017). "Recently, soluble β-glucan has been reported to induce tumor regression in synergy with TLR9 agonist via DC-mediated immunity." (PMID 29163499, 2017). "Toll-like receptor 9 (TLR9) is an innate immune system DNA-receptor that regulates tumor invasion and immunity in vitro." (PMID 28886076, 2017). "Studies have revealed that treatment with CpG oligodeoxynucleotides (CpG ODNs), chemically synthesized TLR9 agonists, leads to tumor regression as a result of T cell- or natural killer (NK) cell-dependent lysis of tumor cells." (PMID 28241765, 2017). "Of interest, relative to inoculation of α-GalCer-loaded tumor cells alone, coadministration of α-GalCer-loaded tumor cells and TLR9 agonists augments the antitumor response." (PMID 28798749, 2017). "Remarkably, instead of TLR9, intratumoral administration of TLR7 ligand activated tumor associated pDCs and provoked a strong tumor regression effect." (PMID 29050360, 2017). "The aim of this study was to evaluate tumor TLR9 expression among AA TNBC patients and to assess its relationship to survival and recurrence in this patient population." (PMID 28886076, 2017). "During hypoxia, HMGB1 translocates from nucleus to the cytosol, binds to mtDNA released from damaged mitochondria, and subsequently activates TLR9 signaling pathway to promote tumor cell proliferation." (PMID 28969092, 2017). "It has been shown that the activation of TLR9 by CpG activated pDCs, which were capable of initiating effective anti-tumor immunity through the activation of NK cells, mDCs and CD8+ T cells in a mouse melanoma model." (PMID 28052019, 2017). "For example, TLR5 and TLR9 exhibit anti-tumoral properties by activating immune cells and having a direct cytotoxicity effects on tumor cells." (PMID 28632155, 2017).
tumor (continued). "Another intriguing example of CpG-mediated anti-tumour effect was reported afterintratumoural injection of the TLR9 agonist CpG, along with anti-OX40Land/or anti-CTLA4 antibodies, to eliminate TREGs in the tumourmicroenvironment." (PMID 28791124, 2017). "CpG-ODNs are synthetic TLR9 agonists and have been exploited as adjuvants for anti-tumour and vaccine therapeutics." (PMID 27558877, 2016). "The dSLIM® and particularly dSLIM2006‐PD efficiently combine sequence parameters with structural parameters to form efficient TLR9 agonists with highly efficient anti‐tumor activity." (PMID 27980779, 2016). "In particular, activation of the TLR9 pathway promotes the development of anti-tumor T-cell responses." (PMID 27092172, 2016). "We also performed tumor oxygen measurements at day 24, as our previous studies suggested that hypoxia helps to maintain TLR9 expression difference between control and TLR9 shRNA MDA-MB-231 tumors." (PMID 27888633, 2016). "Kortylewski and colleagues developed an aptamer-siRNA conjugate to selectively target the toll-like receptor 9 (TLR9) expressing immune cells of the tumor microenvironment." (PMID 27827876, 2016). "We also demonstrated that in some cases BPs actually promoted tumor cell growth and this effect was lost with decreased TLR9 expression." (PMID 27888633, 2016). "PaCaDD135 tumor cells expressed predominantly TLR9 and to a lesser extent TLR2 and -4 (77.0%, 12.1% and 1.4% respectively) (bottom)." (PMID 27941651, 2016). "We show here, rather surprisingly, that tumor TLR9 expression status affects the direct tumor responses to BPs in vitro and in vivo." (PMID 27888633, 2016). "In some tumor types, TLRs promote tumor proliferation and survival, as seen with TLR9 agonists, Pam2 lipopeptides (TLR2/6 ligands), and flagellin." (PMID 27708223, 2016). "Immunization with MIS416, a novel adjuvant comprising NOD-2 and TLR9 stimulatory ligands, significantly prolonged survival in tumor-bearing mice." (PMID 25888637, 2015). "A TLR9 agonist enhances the anti-tumor immunity of peptide and lipopeptide vaccines via different mechanisms." (PMID 26215533, 2015). "In fact, sterile tissue injury or tumor irradiation can stimulate TLR9 signaling in vivo through release of natural TLR9 agonists such as mitochondrial DNA." (PMID 26046794, 2015). "Our study points the possible metastasis promoting effect of the tumor originated DNA via TLR9 independent pathway due to the overexpression of metastasis associated genes, metabolic genes and signaling pathways driving promoting cancer cell invasion." (PMID 26133168, 2015). "This study also revealed that increased TLR9 expression correlated with advanced tumor size, while high TLR5 expression was associated with a lower tumor grade." (PMID 25999952, 2015). "Further in vivo studies will elucidate effects of inhibiting TLR9-mediated signaling, which should trigger differentiation of cancer-propagating cells into tumor cells with potentially greater sensitivity to standard therapies." (PMID 26046794, 2015). "In conclusion, a single administration of recombinant lipoprotein induced strong anti-tumor immunity in the presence of a TLR9 agonist." (PMID 24642245, 2014). "The TLR7/8 agonist 3M-052 and the TLR9 agonist CpG ODN both trigger innate immune responses that support the induction of tumor-specific immunity." (PMID 24982761, 2014). "While, overall, there was relatively little TLR9 expression in dysplastic oral tissue, there was significantly more than in normal oral mucosa and increased expression of TLR9 had earlier been found to correlate with increased tumor cell proliferation in OSCC." (PMID 25309546, 2014). "Overall, the results from this trial are encouraging and suggest a potential role for TLR9-targeted immunoactivation with MGN1703 in maintenance therapy of metastatic CRC after an effective first-line regimen inducing a tumour response." (PMID 24816725, 2014).